GNA15 (G protein subunit alpha 15)
Description:
Member of the G protein alpha subunit family that plays a crucial role in intracellular signaling. Functions as a molecular switch, transducing signals from G protein-coupled receptors (GPCRs) to downstream effectors. In collaboration with the adapter protein TTC1, promotes HRAS activation and ERK1/2 phosphorylation independently of phospholipase Cbeta signaling. Also initiates EMR2-mediated signaling, leading to activation of Akt, MAPK, and NF-kappa-B, which in turn drives macrophage differentiation and inflammatory responses.
Synonyms: GNA16; HG1L
Tractability: Small molecule: a high-quality ligand is known. Antibody: its Gene Ontology location is reachable by antibodies, with high confidence. PROTAC: ubiquitination databases record sites on it; its protein half-life has been measured; a small molecule that binds it is known.
Gene: Protein-coding gene on chromosome 19 (3,136,033 to 3,163,749, forward strand). Ensembl gene ENSG00000060558.
Pathways (Reactome):
Hemostasis: ADP signalling through P2Y purinoceptor 1; Thrombin signalling through proteinase activated receptors (PARs); Thromboxane signalling through TP receptor
Signal Transduction: G alpha (q) signalling events; G-protein activation; PLC beta mediated events
Metabolism: Acetylcholine regulates insulin secretion; Fatty Acids bound to GPR40 (FFAR1) regulate insulin secretion
Metabolism of proteins: Cooperation of PDCL (PhLP1) and TRiC/CCT in G-protein beta folding
Gene Ontology:
Molecular function: G protein-coupled receptor binding; GTP binding; GTPase activity; G-protein beta/gamma-subunit complex binding; guanyl nucleotide binding
Biological process: calcium-mediated signaling; phospholipase C-activating G protein-coupled acetylcholine receptor signaling pathway; G protein-coupled receptor signaling pathway; phospholipase C-activating G protein-coupled receptor signaling pathway; signal transduction
Cellular component: heterotrimeric G-protein complex; plasma membrane; synapse
Genetic constraint (gnomAD): Loss-of-function variants: 23 observed, 35.95 expected, observed/expected ratio (o/e) 0.64, 90% interval 0.46 to 0.91. The upper end of that interval is the gene's LOEUF score, 0.91, which puts it in group 3 of 6, group 1 being the genes least tolerant of losing a copy. Missense variants: 519 observed, 504.87 expected, observed/expected ratio (o/e) 1.03, 90% interval 0.96 to 1.11. Synonymous variants: 225 observed, 201.82 expected, observed/expected ratio (o/e) 1.11, 90% interval 1 to 1.25.
Homologues: Orthologues: chimpanzee GNA15 (100% identical), dog GNA15 (95% identical), pig GNA15 (95% identical), rat Gna15 (86% identical), mouse Gna15 (85% identical), macaque GNA15 (84% identical), tropical clawed frog gna15 (57% identical), zebrafish gna15.1 (56% identical), zebrafish gna15.2 (53% identical), Drosophila melanogaster CG30054 (48% identical), zebrafish gna15.3 (48% identical), Drosophila melanogaster CG17760 (47% identical), and 18 more. Paralogues in human: GNA11 (54% identical), GNAQ (54% identical), GNA14 (53% identical), GNAI1 (42% identical), GNAI2 (42% identical), GNAI3 (42% identical), GNAO1 (42% identical), GNAT1 (42% identical), GNAT2 (41% identical), GNAT3 (41% identical), GNAZ (41% identical), GNA13 (40% identical), and 3 more.
Diseases named in the same sentence as GNA15 in open-access papers:
GNA15 is named in the same sentence as 34 diseases in open-access papers, as found by Europe PMC text mining. Sharing a sentence is not in itself a finding about the gene and the disease. The quoted sentences say what the papers report.
ovarian carcinoma (5 papers, 2017 to 2025). A malignant neoplasm originating from the surface ovarian epithelium. "The role of HRH4 in breast cancer cell proliferation and expression of GNA15, and different chemokines in small intestinal neuroendocrine neoplasia, pancreatic ductal adenocarcinoma, and ovarian cancer was also observed." (PMID 36902343, 2023). "The relationship between increased expression of GNA15, early relapse, and poor survival in SOC may be attributed to the induction of a stem cell-like phenotype in human ovarian cancer cells through the downregulation of AKT activity." (PMID 38685095, 2024). "GNA15 is known to play as an oncogene in several tumors, such as gastroenteropancreatic neuroendocrine neoplasia (GEP-NEN), liver cancer, pancreatic ductal adenocarcinoma and ovarian cancer." (PMID 34552875, 2021). "A study based on bioinformatics analysis suggested that GNA15 may be related to ovarian cancer, but it has not been clinically and experimentally verified." (PMID 34552875, 2021).
acute myeloid leukemia (3 papers, 2019 to 2026). Acute myeloid leukemia (AML) is a group of neoplasms arising from precursor cells committed to the myeloid cell-line differentiation. "This is consistent with other studies on GNA15’s role in acute myeloid leukemia cell proliferation, further advancing our understanding of GNA15’s mechanisms in CRC." (PMID 41488280, 2026).
leukemia (3 papers, 2021 to 2024). A malignant (clonal) hematologic disorder, involving hematopoietic stem cells and characterized by the presence of primitive or atypical myeloid or lymphoid cells in the bone marrow and the blood. "Moreover, CD312 could bind to GNA15 in CD3 + T cells to promote the proliferation in leukaemia cells through activating the phosphorylation of ERK, JNK and p38 pathways." (PMID 39656442, 2024). "Moreover, CD312 could bind to GNA15 in CD3+ T cells to promote the proliferation in leukaemia cells through activating the phosphorylation of ERK, JNK and p38 pathway." (PMID 39656442, 2024). "The BrdU staining assay revealed that the proliferation of leukaemia cells was enhanced in the CD312‐overexpressed CD3+ T cells group via the phosphorylation of ERK, JNK and p38, whereas it was decreased by GNA15 knockdown in the co‐culture system." (PMID 39656442, 2024). "The BrdU staining assay showed that the proliferation of leukaemia cells was increased in the CD312‐overexpressed CD3+ T cells group, while it was downregulated by GNA15 knockdown." (PMID 39656442, 2024). "To clarify whether GNA15 is involved in a CD312‐mediated bone marrow immune microenvironment, we used a co‐culture system to detect the proliferation and apoptosis of leukaemia cells." (PMID 39656442, 2024). "Pancreas, bile duct, and to a lesser extent, lung cancer cells are distinct among non-hematopoeitic lineages for ectopic GNA15 expression at high levels similar to leukemia." (PMID 34290274, 2021).
lung carcinoma (2 papers, 2013 to 2021). "In addition, we also searched for somatic copy number variations (CNV) at GNA15/16 locus in human lung cancers." (PMID 24204697, 2013).
pancreatic ductal adenocarcinoma (2 papers, 2023 to 2024). An infiltrating adenocarcinoma that arises from the epithelial cells of the pancreas. "GNA15 has been identified as highly expressed in small intestinal neuroendocrine neoplasia and pancreatic ductal adenocarcinoma, correlating with poor survival." (PMID 38685095, 2024). "In contrast, expression of GNA15 in the pancreas was limited to transformed cells and occurred in the initial stages of pancreatic ductal adenocarcinoma progression." (PMID 36902343, 2023).
Sepsis (2 papers, 2022 to 2023). Sepsis is defined as life-threatening organ dysfunction caused by a dysregulated host response to infection. "The “Sepsis Metascore” subpanel on another hand, consists of a sepsis-specific transcripts including CEACAM1, C3AR1, GNA15, and HLA-DPB1 which have previously been linked to sepsis." (PMID 35186993, 2022).
acute leukemia (1 paper, 2021). A clonal (malignant) hematopoietic disorder with an acute onset, affecting the bone marrow and the peripheral blood. "In our study, we found that the expression of GNA15 in acute leukemia was significantly higher than that in controls, and the expression of GNA15 in AML was significantly higher than that in ALL." (PMID 34552875, 2021). "RT-qPCR and Western blot analysis revealed that GNA15 is highly expressed in nearly all acute leukemia cell lines tested while lowly expressed in lymphoma and myeloma cell lines and normal controls." (PMID 34552875, 2021).
Alzheimer disease (1 paper, 2021). A progressive, neurodegenerative disease characterized by loss of function and death of nerve cells in several areas of the brain leading to loss of cognitive function such as memory and language. "Given that G protein-coupled receptors (GPCRs) mediate the cellular response to most hormones/neurotransmitters, it is unsurprising that GPCR-related genes converge on normal aging (GNA15) and Alzheimer’s disease (GNAS, GNB5)." (PMID 34002691, 2021).
asthma (1 paper, 2026). "The remaining three IL-22 activators were all candidate genes for asthma alone: GNA15, SESN1, and GATA3, of which only GATA3 has been previously reported to directly activate IL-22 in ILC3s113." (PMID 41573945, 2026).
colorectal adenocarcinoma (1 paper, 2023). The most common type of colorectal carcinoma. "A similar effect can be expected in the presented study, in which GNA15 in subsequent stages of colorectal adenocarcinoma had increased expression." (PMID 36902343, 2023).
developmental delay (1 paper, 2017). "Genes such as GNA15 and SDHAP3 that contained maternal smoking-associated DMRs displayed a developmental delay in mRNA up-regulation in smoking exposed." (PMID 28149327, 2017).
endometrial adenocarcinoma (1 paper, 2018). "Besides, LPAR and GNA15 genes showed some roles in cancer signaling for endometrial adenocarcinoma and esophagus tumor, respectively." (PMID 30774811, 2018).
endometrial carcinoma (1 paper, 2022). A malignant tumor arising from the epithelium that lines the cavity of the uterine body. "Eight IRGs were incorporated to construct a nomogram for survival prediction in endometrial carcinoma patients, including CCR7, GNA15, GPR132, LTA, MYC, NOD2, P2RX4 and P2RY2." (PMID 36207698, 2022). "Among these genes, CCR7, MYC and NOD2 have been reported in a large number of tumor studies, including endometrial cancer, while P2RX4, GNA15, and GPR132 genes have few molecular biological experiments to verify their role in endometrial cancer progress." (PMID 36207698, 2022).
heart failure (1 paper, 2020). Inability of the heart to pump blood at an adequate rate to meet tissue metabolic requirements. "The SNP with the lowest P value was rs74675399 (chr19p13.3, P = 1.21 × 10−7; OR = 6.36), located in the GNA15 gene, previously associated with heart failure." (PMID 32066683, 2020).
lung adenocarcinoma (1 paper, 2013). A carcinoma that arises from the lung and is characterized by the presence of malignant glandular epithelial cells. "Strikingly, the mutation status of GNA15/16 locus was 1.22% for homozygous deletions and 53.14% for single copy deletions in human lung adenocarcinoma patients and 0.96% for homozygous deletions and 41.34% for single copy deletions in human lung squamous carcinoma patients." (PMID 24204697, 2013).
myocarditis (1 paper, 2020). Myocarditis is a condition that is characterized by inflammation of the heart muscle (myocardium). "The locus with the lowest associated P value was located within intron 2 of the GNA15 gene and is associated with six-fold increase in susceptibility to clozapine-induced myocarditis." (PMID 32066683, 2020).
neuroblastoma (1 paper, 2017). Neuroblastoma (NB) is the most common solid, extracranial childhood tumor. "Notably, GNA15 is transcriptionally modifiable by acute doses of nicotine in neuroblastoma cell lines, indicating nicotine as a potential causative agent." (PMID 28149327, 2017).
pancreatic adenocarcinoma (1 paper, 2021). "The Cancer Genome Atlas program (TCGA) shows for pancreatic adenocarcinoma (PAAD) that among 16 Gα genes, only elevated expression of GNA15 was associated with worse prognosis." (PMID 34290274, 2021).
tongue cancer (1 paper, 2015). A malignant neoplasm affecting the tongue. "After comparison between tongue cancer and corresponding normal samples, GNA15, PPP2R3A, LAMB3, HSPA2, and MAP4K3 were identified as five top-ranking genes." (PMID 26336805, 2015).
tumor (9 papers, 2008 to 2026). "Through the integration and analysis of multiple datasets, including immunohistochemical validation and single-cell analysis, it has been shown that GNA15 is highly expressed in CRC tissues compared to adjacent non-tumor tissues, indicating its potential as a screening diagnostic target." (PMID 41488280, 2026). "Additionally, the expression levels of GNA15 have been implicated in the effectiveness of anti-tumor chemotherapeutic medicines." (PMID 38685095, 2024). "GNA15 has been shown to mediate the effects of oncogenic microRNAs (miRNAs), such as miR-211-5p, which enhance tumor cell migration and invasion by modifying the immune functions of the TME." (PMID 41488280, 2026). "The expression level of GNA15 in tumor tissues was significantly higher than that in adjacent tissues (P = 2.74641 × 10-85)." (PMID 41488280, 2026). "GNA15 plays an important role in cancer-related research and plays a key role in the migration and invasion of tumor cells as well as in the malignant development of cancer, which makes it a promising therapeutic target for research." (PMID 41488280, 2026). "Characterization of GNA15 expression in paired normal tissue and tumor samples revealed exocrine pancreas had among the highest differential induction of GNA15 in cancer." (PMID 34290274, 2021). "For example, some tumor cells may use antigen-antibody binding to escape from the immune system, and GNA15 may play a facilitating or regulating role in this process, thus affecting the development of CRC." (PMID 41488280, 2026). "The correlation between GNA15 expression and tumor microenvironment (TME) was studied." (PMID 41488280, 2026). "GNA15 is of great significance in the malignant behavior of tumor cells and the development of CRC, and its in-depth study is expected to provide new directions and strategies for cancer treatment, and it is worthwhile to further explore the possibility of its use as a therapeutic target." (PMID 41488280, 2026). "The upregulation of GNA15 may be closely related to tumor cell proliferation and modulation of the TME, suggesting its potential application in CRC diagnosis and treatment." (PMID 41488280, 2026). "In view of the anti-tumor mechanism of B cells in CRC, the high expression of GNA15 may inhibit the development of B cells in the direction of anti-tumor function." (PMID 41488280, 2026). "This indicates that the conclusion of high expression of GNA15 in tumor cells is reliable." (PMID 41488280, 2026). "Overall, these findings underscore the multifaceted functions of GNA15 in tumor cellular processes." (PMID 38685095, 2024). "The analysis of biological data sets, primary and xenografted human tumor samples, and clinical follow-up shows that elevated expression is associated with poor prognosis for GNA15, but not any other GNA gene." (PMID 34290274, 2021). "Second, while in vitro experiments validated GNA15’s pro-proliferative role, in vivo models recapitulating tumor-stroma interactions were lacking, which limits mechanistic insights into its microenvironment-modulating effects." (PMID 41488280, 2026). "TMEM108 and C3orf47 were positively correlated with tumor grade and eight genes, including LAD1, TIF1, FGF11, carbonic anhydrase 12 (CA12), G protein subunit α15 (GNA15), junction plakoglobin (JUP), plakophilin 1 (PKP1) and PPARD, were negatively correlated with the tumor grade of ESCC patients." (PMID 28904855, 2017). "As expected, GNA15 presented a non-significant differential expression pattern when tumor samples were compared to normal tissues." (PMID 19014460, 2008). "Given the positive correlation between GNA15 expression and B cell infiltration, it is hypothesized that GNA15 may regulate B cell-related anti-tumor processes rather than inhibiting B-cell function." (PMID 41488280, 2026).
cancer (8 papers, 2013 to 2026). A tumor composed of atypical neoplastic, often pleomorphic cells that invade other tissues. "These associations are likely related to the abnormal GNA15 expression in PDAC cancer cells, whereas GNAL, GNAO1, and GNA14 are preferentially expressed in normal pancreas, which is progressively lost as transformed tissue prevails." (PMID 34290274, 2021). "This indicates the role of GNA15 in facilitating the transfer of metastatic capabilities between cancer cells." (PMID 41488280, 2026). "Taking into consideration the cancer development process, the following histaminergic genes stood out: GNA15, HRH1-HRH4, MAOA, WASF2, along with inflammation-related genes: AEBP1, CXCL1, CXCL2, CXCL3, CXCL8, SPHK1, and TNFAIP6." (PMID 36902343, 2023). "The last two have decreased expression in all cancer stages compared to the control, while GNA15 has increased expression." (PMID 36902343, 2023). "There are few studies on GNA15, and its effect on cancer was reported even less frequently." (PMID 34552875, 2021). "Correlation analysis also shows that the following histaminergic transcripts: GNA15, HRH2, MAOA, WASF2, and those related to inflammation: AEBP1, CXCL1, 2, 3, and 8, SPHK1, and TNFAIP6 play an important role in cancer tissue." (PMID 36902343, 2023).
adenocarcinoma (1 paper, 2021). A common cancer characterized by the presence of malignant glandular cells. "We sought to describe the distribution of GNA15 in adenocarcinoma from human pancreatic specimens and to analyze the mechanism driving abnormal expression and the consequences on signaling and clinical follow-up." (PMID 34290274, 2021).
hematological malignancies (1 paper, 2021). "We quantified the transcriptional level and protein level of GNA15 in cell lines of hematological malignancies." (PMID 34552875, 2021).
GNA15 also shares sentences with these, for which no sentence is quoted: COVID-19 (2 papers); melanoma (2); Acute Lymphoblastic Leukaemia (1); breast carcinoma (1); chronic pancreatitis (1); colorectal cancer (1); esophagus tumor (1); lymphoma (1); myeloma (1); pancreatic cancer (1); pancreatitis (1).